CD99 (CD99 molecule (Xg blood group))
Diseases named in the same sentence as CD99 in open-access papers (continued):
Sharing a sentence is not in itself a finding about the gene and the disease.
tumor (continued). "Immunohistochemistry showed that the tumor cells had focal membranous expression of CD99, nuclear/cytoplasmic expression of B-cell lymphoma 2, and cytoplasmic/membranous expression of smooth muscle actin and CD34, consistent with an intermediate-grade spindle cell sarcoma." (PMID 35797605, 2022). "In addition, Ki67 labeling index was up to 80% in tumor hotspot areas and immunohistochemistry showed a strong expression of CD99 in myxoid and more densely packed tumor areas, whereas staining of the remaining thyroid follicles was negative." (PMID 35876910, 2022). "But untypically in this case, the tumor cells were positive for CD99." (PMID 36452830, 2022). "The tumor cells also showed positive signal in the immunohistochemical reaction for CD99." (PMID 36414742, 2022). "In addition, the immunohistochemical results showed the altered staining patterns of BCOR, bcl2, CyclinD1, TLE1, AR, SMA, CD117, STAB2, CD56, and CD99 in tumor tissues after chemotherapy." (PMID 35568949, 2022). "Immunohistochemistry (IHC) analysis showed the tumour to be positive for CD99, NKX 2.2, and MIC2." (PMID 35755520, 2022). "Notably, comparable tumor-derived luminescence was detected when injecting GPR64- or CD99-directed, 2.2-pseudotyped compared to VSV-G-pseudotyped lentiviruses that served as positive control." (PMID 36229873, 2022). "Consequently, histopathology and immunohistochemical examination of the markers S-100, CD99, and Ki-67 showed that the tumor cells stained positively for S-100 and CD99." (PMID 35354472, 2022). "Because of this, a minor set of five additional markers (CD99, GD2, CD271, EpCAM, and numyogenin) was selected from all tumor-associated proteins investigated, for the differential diagnosis between the four major subgroups of extracranial SRCT vs. other pediatric tumors." (PMID 34638431, 2021). "Furthermore, the proliferation marker Ki67 was localised to the CD99-expressing tumour cells, and quantification of Ki67+ cells showed a significantly higher tumour burden in the mice implanted with CD99-depleted MDA-MB-231 cells." (PMID 34374417, 2021). "Leucocytes use CD99 to cross endothelial barriers, suggesting that tumour cell CD99 might regulate TEM during metastasis." (PMID 34374417, 2021). "Expression of CD99 was reduced in both tumour and EC using siRNA." (PMID 34374417, 2021). "Thus, despite an established role for CD99 in leucocyte TEM, the function of CD99 in tumour cell TEM and the metastatic pathway is currently ill-defined." (PMID 34374417, 2021). "In contrast, loss of EC CD99 did not significantly decrease tumour cell adhesion and, at a late time point, adhesion was significantly increased, revealing a non-equivalent role for CD99 in these tumour cells and interacting endothelium." (PMID 34374417, 2021). "However, CD99 has both pro- and anti-tumour activity, and our data suggest that this results in part from its functional linkage to CDC42 and the diverse signalling pathways downstream of this Rho GTPase." (PMID 34374417, 2021). "Differential activity of CD99 in tumour cells and healthy primary leucocytes likely reflects the number and nature of the different cell surface molecules implicated in the adhesion/TEM pathways and the relative expression of these molecules by the migrating cell type." (PMID 34374417, 2021). "Furthermore, these cells retain the EWSR1-ETS fusion transcript and cell surface expression of CD99 with the tumours from which they were derived." (PMID 34403115, 2021). "The solvent-treated control tissue showed numerous CD99/Ki-67 positive tumor foci." (PMID 34640378, 2021). "Moreover, compared with ductal-normal and ductal-tumor cells, CD55_ADGRE5, CD99_PILRA, ANXA1_FPR3 interactions were drastically upregulated in the malignant cells." (PMID 35087839, 2021). "In this context, >90% of SFT express CD34 and STAT6, while a smaller percentage of tumours may be positive for CD99 (70%), EMA (20%), smooth muscle actin (20%) and BCL-2 (30%)." (PMID 34849218, 2021).
tumor (continued). "ECs also express CD99 and we used RNAi to determine whether it was the tumour or EC CD99 that regulated these adhesion events." (PMID 34374417, 2021). "However, luciferase signals in the lungs of animals injected with control tumour cells exceeded signals from CD99-depleted cells by ∼fivefold at the 6-h time point (P=0.067)." (PMID 34374417, 2021). "We speculate that, in a primary tumour, small numbers of cells with reduced CD99 expression gain migratory and TEM activity, allowing them to enter the vasculature." (PMID 34374417, 2021). "Furthermore, consistent decrease at the transcriptomics level and in the urine peptide profiles was demonstrated for CD99, which is negatively regulating Cdc42 in tumour cells." (PMID 31900160, 2020). "Indeed, 40% of non-EwS cases examined in the current study (128/320 samples, representing 11 distinct tumor entities) exhibited a strong CD99 immunostaining (IRS >8)." (PMID 32164354, 2020). "On IHC, tumour cells were positive for vimentin, cytokeratin, and CD99." (PMID 33520482, 2020). "Over 90% of tumor biopsies expressed high levels for membranous CD99." (PMID 32821345, 2020). "The tumour was positive for CD99, ERG, CD56, Synaptophysin, PanCK, Cam5.2." (PMID 32450834, 2020). "Anti-CD99 antibodies exert additive/synergistic effects when combined with conventional agents, such as doxorubicin or vincristine, and are effective even against chemoresistant tumor cells." (PMID 32295254, 2020). "Our results show that CD99 is also highly expressed in the tumor vasculature of most solid tumors." (PMID 31001265, 2019). "Thus far, the current knowledge of CD99 function derives from experiments of CD99 activation by agonist monoclonal antibodies, in hematopoietic and tumor cells." (PMID 30845661, 2019). "In addition, knockdown of CD99 in EWS tumor cells reduced in vivo tumor growth in mouse xenograft experiments." (PMID 31001265, 2019). "CD99 is also expressed on the surface of ES cells, making it an attractive tumor target." (PMID 31275859, 2019). "Unfortunately, CD99 is not only expressed on ES but also on normal human tissues including the testis, gastric mucosa, prostate, and hematopoietic tissues, with potential of off-tumor, on-target bystander toxicities when used in humans." (PMID 31275859, 2019). "It has been reported that CD99 can affect the migration, invasion and metastasis of tumor cells." (PMID 31001265, 2019). "The fact that these proteins were detected as conserved proteins in the analysis of three different co-culture experiments indicated that CD73 and CD99 were the proteins that bound most reproducibly with emmprin under conditions of co-culture of tumor cells and fibroblasts." (PMID 31510956, 2019). "Indeed, all the EWS cells released CD99, and its levels in cell supernatants were consistent with the cellular expression of the molecule and were positively correlated with tumor cell aggressiveness." (PMID 31209202, 2019). "Moreover, since CD99 is a specific marker for ES found in the cytoplasmic membrane of 100% ES tumour cells, the IHC double-staining method was applied to detect the co-expression of TNC and CD99 in ES tissue." (PMID 31649319, 2019). "In tumors, CD99 isoforms have also been related to different functions in tumor malignancy." (PMID 30845661, 2019). "Immunohistochemically, the tumor cells were positive for CD99 and vimentin." (PMID 31875190, 2019). "Previously, it has been reported that the expression of CD99 in lung cancer tumor stroma is associated with poor prognosis, which, together with our observation of CD99 with emmprin, suggests the possibility that CD99 also contributes to an interaction between tumor and stroma." (PMID 31510956, 2019).
tumor (continued). "Also, a monoclonal antibody against CD99 (0662 Mab) combined with doxorubicin showed enhanced inhibition of EWS tumor growth and metastasis formation in a xenograft model." (PMID 31001265, 2019). "In addition, CD99 expression on cultured endothelial cells was induced by nutrient deprivation, which suggests that expression of CD99 in the tumor vasculature is most likely regulated by microenvironmental stress." (PMID 31001265, 2019). "Some reports demonstrated that tumor cells were positive for CD99 in agreement with our result." (PMID 30206803, 2019). "Our results suggest that the addition of the anti-CD99 treatment could be beneficial when irinotecan alone is less effective, possibly depending on tumor growth rate." (PMID 31434953, 2019). "The tumor however was double positive for CD99 and TLE1 which made it difficult to discriminate it from the myxoid variant of SS based on histopathological examination and immunophenotype alone, and genetic analysis for SYT gene rearrangement was required to reach a definitive diagnosis." (PMID 30410809, 2018). "In fact, exosome-mediated diffusion of the effects initiated by CD99 abrogation suggests that even a partial delivery of CD99 small interfering RNA (siRNA) may have a broad effect on an entire tumor cell population." (PMID 29534016, 2018). "Accordingly, anti-CD99 antibodies exert additive/synergistic effects when combined with conventional agents, such as doxorubicin or vincristine and are effective even against chemoresistant tumor cells." (PMID 29305692, 2018). "Knocking down CD99 expression by siRNA in cell lines derived from these tumors significantly decreased cell migration, further suggesting that CD99 may contribute to the infiltrative ability of tumor cells." (PMID 29534016, 2018). "CD99 was found to be highly expressed in ependymomas, in malignant gliomas, and in astrocytomas, where its detection can help discriminate among tumor grades, with a differential subcellular distribution according to the malignancy stage." (PMID 29534016, 2018). "We hypothesized that CD99 cleavage by meprin β plays a role in tumor development based on three reasons." (PMID 28903388, 2017). "In contrast, a significant number of tumour cells expressed CD99 antigen." (PMID 27019694, 2016). "The discovery that anti-CD99 0662mAb exerts its anti-tumor action by enhancing IGF-1R/RAS/Rac1 activity may seem paradoxical." (PMID 27835596, 2016). "Immunohistochemistry showed tumour cells staining positive for CD-99: specific stain for ES." (PMID 27895949, 2016). "Moreover, the most intense NPY immunostaining among all cell fractions tested was seen in groups of CD99-positive tumor cells invading the bone." (PMID 25714031, 2015). "Immunohistochemically, tumor was bcl-2 and CD99+, SMA and S-100 -." (PMID 26449317, 2015). "Several studies have also found CD117 and CD99 positivity in cases of MCC, and CD44-positive cases may correlate with the high risk of tumor metastasis." (PMID 25663881, 2015). "Immunohistochemically, the tumor cells showed diffuse membrane positivity for CD99, Syn and FLI1." (PMID 25780425, 2015). "The tumor also shares expression of glycoprotein surface antigen mic2/CD99." (PMID 24847440, 2014). "The expressions of Ki-67 and CD99 are quite uncommon and might be related to more aggressive tumor growth." (PMID 24083035, 2013). "Immunohistochemistry showed strong staining of the tumour cells for vimentin and CD99." (PMID 23379545, 2013). "Moreover, RMS cases were also CD45−, CD56+lo, CD90+ and CD57−; two expressed CD81+, CD9+ and CD58+ and one was partially positive for CD99 (40% of tumor cells ), a phenotypic pattern which was specific for this tumor subtype." (PMID 23472067, 2013). "Tumor cells expressed markers of mesenchymal tissue Vim, CK, and CD99." (PMID 24339974, 2013). "Immunohistochemistry indicated that tumor cells were positive for Vimentin and CD99 (Mic-2)." (PMID 23329974, 2012).
tumor (continued). "The tumor cells were positive for CD99, bcl-2 and focally reactive for CK, EMA in all five cases." (PMID 22862905, 2012). "Moreover, the engagement of CD99 improves the efficiency of the conventional chemotherapeutic agents and reduces tumor growth along with a significant delay of metastasis." (PMID 21909426, 2011). "Instead, the tumor cells showed striking CD99, synapthophysin and desmin immunoreactivity." (PMID 20598147, 2010). "To assess whether the superior memory phenotype and functional persistence observed in vitro could be translated to an in vivo setting, we evaluated the tumor-suppressive function and differentiation states of CD99 CAR-T cells in a subcutaneous A673 xenograft model." (PMID 41596259, 2026). "Collectively, these findings suggest that CD99- and MIF-mediated signaling may represent important components of canine immune homeostasis that may extend beyond the steady state to inflammatory or tumor-associated contexts." (PMID 41488614, 2025). "In contrast, CD99 signaling may enhance T cell cytotoxicity and induce tumor cell apoptosis." (PMID 40260248, 2025). "The high expression of CD99 on the cell surface and its crucial role in sustaining tumor malignancy are the two primary reasons why it has garnered significant interest over the years for developing new targeted therapies using mAbs for tumors that overexpress CD99." (PMID 40427525, 2025). "Moreover, the SFT tumor cells were positive for CD99 and Bcl-2." (PMID 39206171, 2024). "However, in a recent study, a team confirmed the presence of CTCs in ES patients based on the immunodetachment of CD99+ tumor cells and magnetic beads, followed by molecular analysis to detect specific fusion transcripts from chromosomal translocations, which provides a new way of detecting CTCs." (PMID 39617822, 2024). "The presentation of the subgroups on the CD99 signaling pathway reveals that the C3 PLP2+ Tumor EPCs subgroup has the highest quantity and centralization score, providing evidence of a robust association between this pathway and the C3 PLP2+ Tumor EPCs subgroup." (PMID 38482016, 2024). "Immunofluorescent detection of tissue samples with high and low CuAS showed that VEGFA and CD99 were also highly expressed in tissues with high CuAS, and the results were opposite in tissues with low CuAS, which provided a new idea for us to intervene in cuproptosis-related tumor cells." (PMID 36647156, 2023). "Furthermore, some tumor cell groups were weakly positivity for CD99." (PMID 36414742, 2022). "Thus, the expression of CD99 in combination with E-cadherin and β-catenin might be valuable combinational tumor markers for the diagnosis of SPTs and pNENs." (PMID 36271376, 2022). "Tumour-mediated loss of barrier integrity was independent of CD99 expression at the 1 h time point." (PMID 34374417, 2021). "Tumour cells interacting with the endothelium altered their morphology from spherical structures (with high circularity) towards a spread and more flattened appearance, and depletion of tumour cell CD99 increased this spreading phenotype, an effect that was statistically significant at 4 h." (PMID 34374417, 2021). "Importantly, the spreading of tumour cells on ECs was inhibited by the depletion of CDC42, and the enhanced spreading of tumour cells seen upon CD99 depletion was also CDC42 dependent, with statistically significant differences in phenotype observed at the 4-h time point." (PMID 34374417, 2021). "Further knowledge on the downstream molecular mechanisms, that lead CD99 to modify the cellular actin dynamics, may also enable the identification of other druggable targets for combinatorial therapy and to better improve the outcome of this dreadful tumor." (PMID 30845661, 2019). "In addition, vaccination against CD99 could be used to treat other solid tumors by means of targeting the tumor vasculature." (PMID 31001265, 2019).
tumor (continued). "Therefore, therapeutic strategies to downregulate CD99 may improve tumor respectability and may reduce the probability of tumor recurrence." (PMID 30845661, 2019). "Indeed, CD73 and CD99 were expressed abundantly both in fibroblasts and in tumor cells." (PMID 31510956, 2019). "Also, CD99 has been found to be involved in the migration, invasion and metastasis of tumor cells." (PMID 31001265, 2019). "Furthermore, it is upregulated in cancer suggesting that disruption of normal CD99 protein levels may be favorable for malignant transformation or tumor progression." (PMID 28903388, 2017). "But, nonspecific diagnostic nature of CD99 was reported in several tumor studies." (PMID 24349741, 2013). "Immunohistochemically, the reported eight neoplasms showed variable expression of epithelial markers (AE1/AE3, EMA), six tumors showed MUC4 expression, and four cases were immunoreactive for CD99." (PMID 41341384, 2025). "To further explore the role of the CD99‐driven network in the interaction between APOE‐positive and APOE‐negative tumour cells and immune cells, we focused on these cell types at both the primary thyroid site and lymph node metastasis site." (PMID 39810624, 2025). "In the control group, CD99 signaling predominantly occurred between CD4+ and CD8+ T cells and tumor cells." (PMID 40260248, 2025). "Upon comparing tumor and normal tissues, it was observed that the signal intensity of MHC-2 in Treg cells and CD99 in CD8+ T cells were both bolstered in tumor tissues." (PMID 40723292, 2025). "Bone marrow biopsy revealed the presence of tumor cells, and immunohistochemical staining showed that the tumor cells were positive for CD34, MPO, and CD99, and weakly positive for PAX-5, suggesting a diagnosis of AML." (PMID 41561755, 2025). "CD99 and LEF1 inversely correlated with tumor size and proliferative activity (Ki-67), whereas Cyclin D1 and Ki-67 positively correlated with tumor size and lymphovascular invasion (LVI)." (PMID 40307756, 2025). "In the immunohistochemical examination, tumor cells in SAF show immunoreactivity for CD34, EMA, and CD99." (PMID 39794215, 2025). "When CD99 is knocked down in EWS cells transplanted into immunodeficient mice, it results in terminal neural differentiation, subsequently leading to reduced tumor growth, migration, and incidence of bone metastasis." (PMID 40427525, 2025). "In our patient, histopathological examination confirmed the diagnosis of SFT, with the tumor exhibiting the characteristic features, including positive staining for CD34 and CD99." (PMID 40687408, 2025). "Immunoprecipitation with two membrane-bound proteins (CD99/MIC2, NGFR) allowed for reliable identification of tumour-derived sEVs." (PMID 39797974, 2025). "A separate study has indicated a correlation between the highest levels of CD99 expression in GBM and its relationship with larger, multilobular tumor extensions and increased migratory activity capacity." (PMID 40427525, 2025). "Immunophenotyping found tumor cells that were CK (+), CD56 (+), Syn (+), EMA (+), β-catenin (membrane +), LCA (−), CD99 (−), S100 (−), HMB-45 (−), SOX-10 (−), TTF-1 (−), CDX-2 (−), and CD34 (−), along with a Ki-67 proliferation index of 60–70%." (PMID 41245381, 2025). "The prevailing notion is that the presence of CD99 enhances the oncogenic potential of EWS-FLI1; however, CD99 also plays an active role in maintaining tumor malignancy." (PMID 40427525, 2025). "By immunohistochemistry, the tumor cells are frequently positive for EMA, desmin, and CD99, either diffusely or focally." (PMID 38291529, 2024). "In our study, almost all neoplasms were positive for BCL2, CD99, CD56, FLI1, TLE1, MUC4, and PDGFR alpha." (PMID 39062853, 2024).